YBX3 (Y-box binding protein 3)
Diseases named in the same sentence as YBX3 in open-access papers (continued):
Sharing a sentence is not in itself a finding about the gene and the disease.
tumor (27 papers, 2005 to 2026). "In vivo, USP18 deficiency inhibits xenograft tumor growth by decreasing YBX3 expression and blocking the PI3K/AKT pathway." (PMID 42111157, 2026). "The results also suggest that YBX3 is associated with tumor immune evasion via different mechanisms involving T-cell exclusion in different cancer types and by the tumor infiltration of immune cells." (PMID 36059530, 2022). "Cross comparison of our DEGs to a E2F1 cistrome revealed many E2F1 target genes (E2f7, Rtel1, Myc, Ybx3 and Id3) being downregulated in β1 integrin-deficient tumours, consistent with slow tumour growth phenotype." (PMID 34782719, 2022). "Deficiency of YBX3 expression in NPC cells reduced tumor metastasis by activating PI3K/AKT signaling in vitro and in vivo." (PMID 33816248, 2021). "Since YBX3′s mRNA level in brain is very low and it’s known to play an oncogenic role in cancers, the frameshift mutation of YBX3 in the patient is less likely to drive tumor formation." (PMID 29764516, 2018). "In summary, our findings demonstrate that TTC36 functions as a tumor suppressor in HCC by inhibiting the Ras/MAPK signaling pathway via YBX3/SPRED1 axis." (PMID 41208883, 2025). "The TTC36/YBX3/SPRED1 axis inhibits tumor growth but induces sorafenib resistance via compensatory PI3K/Akt activation." (PMID 41208883, 2025). "Among the diverse pantheon of genes, high expression levels of ybx3 stand in a significant nexus with the pathological staging of tumours, histological grading, TNM staging, and the abundance of immune cell subpopulations." (PMID 39011666, 2024). "A high expression level of YBX3 was significantly correlated with the tumor pathological stage, histological grade, TNM stage, and the abundance of aDC, pDC, Th1, and Treg immune cells." (PMID 37418046, 2023). "Saying this, our WB assay based on nucleocytoplasmic separation and IF staining based on the subcutaneous tumor tissue confirmed that the upregulated BLACAT3 can promote the distribution of YBX3 into the nucleus." (PMID 37612524, 2023). "The results suggested that ccRCC with overexpression of YBX3 had a poorer prognosis, was associated with more male patients, and had an elevated rate of tumor progression to the advanced stages compared to ccRCC with low YBX3 expression." (PMID 37418046, 2023). "A previous study indicates that the upregulation of YBX3 increases cancer cell invasion and tumor chemoresistance." (PMID 36189275, 2022). "For example, the YBX3 was upregulated in various tumor cells, and this upregulation is related to the growth of tumor cells and resistance to chemotherapy." (PMID 33816248, 2021). "NOL12, PABPC1L, RNASE2, RPL22L1, OASL, and YBX3 expression were significantly positively correlated with tumor grade and AJCC stage, while RBM47 expression was negatively correlated with tumor grade and AJCC stage." (PMID 33229623, 2020). "In opposition, YBX3 would display anti-oncogenic effects in squamous cell carcinomas, inhibiting tumor growth and metastasis." (PMID 24885929, 2014). "YBX3 up-regulation has also been reported to play a role in the pathogenesis of gastric cancer, increasing cell invasion and tumor chemoresistance." (PMID 24885929, 2014). "In addition to carrying the Braf gene, chromosome 6 carries several genes that are highly expressed in the LNM and tumor populations (Aqp1, Col1a2, Cav1, Cav2, Ptn, RaRes2, Fkbp9, Actg2, Ybx3, Mgp, Sox5, Kcna1, and Ptms)." (PMID 40571713, 2025). "Additionally, the YBX3 TF, which was predicted to have a reduced activity in CCRCC, has been suggested to be associated with RCC tumor grading." (PMID 37843125, 2023). "Recently, mounting evidence has demonstrated that YBX3 was upregulated in various tumor cells." (PMID 37418046, 2023). "YBX3, a regulator of amino acid transporters and essential for cell growth and proliferation, has been shown to be upregulated in various tumor cells and to participate in tumor progression." (PMID 37418046, 2023).
tumor (continued). "Moreover, the only other study of YBX3 expression in ccRCC reported only modest overexpression in only one out of ten tumor cases studied." (PMID 24885929, 2014). "However, stratification of ccRCC samples according to tumor grade revealed that global YBX3/ZONAB/CSDA expression level is higher in the low-grade tumors and lower in the high-grade tumors." (PMID 24885929, 2014). "Future research should further explore whether YBX3 is influenced by other molecular chaperones or regulatory factors, and investigate the structural basis of the USP5/YBX3 interaction and its dynamic regulation in the tumor microenvironment to promote clinical translation." (PMID 41213937, 2025). "Our research, however, found that, across 39 TCGA databases, YBX3 is associated with tumor infiltration of all kinds of immune cells only in LIHC, indicating that YBX3 might enhance tumor immune evasion and progression of LIHC through dysfunctional T-cell phenotypes." (PMID 36059530, 2022). "In prostate cancer (PCa), the m6A reader PROPER mediates the formation of a complex between YBX3 and YTHDF2, which promotes the degradation of DUSP1, consequently driving tumor metastasis." (PMID 41213937, 2025). "IHC analysis revealed that the protein expression of YBX3 in NPC tissues was significantly higher than that in normal nasopharyngeal tissues, due to the stronger reactivity of YBX3 antibody in tumor cells." (PMID 33816248, 2021). "Collectively, these findings demonstrate that USP5 depletion sensitizes CRC cells to ferroptosis and suppresses tumor progression in both patient-derived organoid and in vivo xenograft models, highlighting the USP5/YBX3-ferroptosis axis as a potential therapeutic target in CRC." (PMID 41213937, 2025). "However, USP5 facilitates the degradation of YBX3, leading to the stabilization of SLC7A11 and thereby promoting CRC cell survival and tumor progression." (PMID 41213937, 2025). "Furthermore, we performed IF staining for YBX3 in subcutaneous tumor samples, and found that BLACAT3 knockdown increased YBX3 distribution in the cytoplasm." (PMID 37612524, 2023). "Y box binding protein 3 (YBX3) is an indispensable factor for protein synthesis, cellular growth, and proliferation, and is intricately involved in the progression of diverse tumor types." (PMID 37418046, 2023). "Furthermore, we identified potential molecular targets based on our expression data in NE-low and immune-oasis tumor subsets, including CD70, ANXA1, ITGB6, TP63, IFI27, YBX3 and CXCR2." (PMID 34200100, 2021). "Moreover, by studying the significance of HEIH and YBX3 on the prognosis of digestive system tumors, we found that they had completely opposite prognostic relationships with the same tumor types, suggesting that there is a suppressive effect between HEIH and YBX3." (PMID 36059530, 2022). "We next analyzed the microarray data of NPC tumor tissues with and without distant metastasis from GEO database to determine whether the expression level of YBX3 was related to NPC metastasis." (PMID 33816248, 2021).
cancer (16 papers, 2006 to 2025). A tumor composed of atypical neoplastic, often pleomorphic cells that invade other tissues. "When we evaluated the diagnostic values of HEIH/YBX3 across cancers among TCGA samples, we found that HEIH played a significant diagnostic role in eight of the 10 cancer types where YBX3 played a significant diagnostic role (AUC > 0.8)." (PMID 36059530, 2022). "Recently, growing evidences have implicated that YBX3 also plays very important functions in the progress of various diseases, such as cancers, nephropathy, and gastrointestinal diseases." (PMID 33816248, 2021). "This study examined the clinical features expression, prognostic value, mutations, along with methylation patterns of three genes from the YBX family (YBX1, YBX2, and YBX3) in 28 different types of cancer." (PMID 38698857, 2024). "It is reported that the aberrant nuclear retention of YBX3 facilitates the proliferation of cancer cells." (PMID 37612524, 2023). "Through qRT-PCR analysis of the cancer cells, subsequent experiments verified that YBX3 was highly expressed in the A498 cell line, whereas the lowest levels of expression occurred in ACHN cells." (PMID 37418046, 2023). "The TISIDB database was used to analyze the role of YBX3 expression in various immune and molecular subtypes of human cancers." (PMID 36059530, 2022). "A total of 15,776 samples across 33 cancer types in TCGA and the GTEx database were analyzed for YBX3 and HEIH expression." (PMID 36059530, 2022). "The pancancer analysis showed that YBX3 expression varies significantly among not only cancer types but also molecular and immune subtypes of the same cancer." (PMID 36059530, 2022). "For other cancer types, YBX3 expression was significantly positively correlated with the infiltration of at least one type of immune cell." (PMID 36059530, 2022). "It has been reported that YBX3 as a transcription factor (TF) is activated in several cancers." (PMID 37612524, 2023). "Moreover, the protein expression level of YBX3 gradually increased with cancer stage and pathological grade." (PMID 36059530, 2022). "Hence, to our knowledge, no existing studies have fully described the significance of HEIH and YBX3 across cancers." (PMID 36059530, 2022). "The correlation between YBX3 expression and the infiltration of three immunosuppressive cell types, including Tregs and CAFs, which have been reported to promote T-cell exclusion among various cancer types, was also further evaluated." (PMID 36059530, 2022). "Our results also suggest that YBX3 expression is associated with immune or chemotherapeutic outcomes in various cancers, and YBX3 exhibited a higher predictive power than two of seven standardized biomarkers for response outcomes and overall survival of immune checkpoint blockade subcohorts." (PMID 36059530, 2022). "In addition, 10,534 samples from the XENA-TCGA database were examined to explore YBX3 expression across cancers in paired samples." (PMID 36059530, 2022). "Our findings suggest that the oncogenic system of HEIH/YBX3 could together serve as a biomarker for cancer detection, prognosis, therapy design, and follow-up." (PMID 36059530, 2022). "Therefore, YBX3 was considered as a cancer prognosis marker." (PMID 33816248, 2021). "Compared to other cancers, USP5’s function shifts from relying on ubiquitination to utilizing the lysosomal pathway, and YBX3 transitions from a pro-survival factor to a ferroptosis-sensitive factor." (PMID 41213937, 2025). "We found that AS-tDR-007333 precipitated with several cancer-related RNA-binding proteins, including HSPB1, DHX9, ACTB, YBX3, and ILF2." (PMID 35526007, 2022). "Among the other genes carrying nonsynonymous mutations that were shared between the brain and lung tumors, the functions of YBX3 and CDT1 have previously been studied in different types of cancers." (PMID 29764516, 2018).
cancer (continued). "Across 33 TCGA cancer types and six cancer subtypes, only LIHC showed a significantly positive correlation between YBX3 expression and the infiltration of all six immune cell types (neutrophils, macrophages, dendritic cells, CD8+ T cells, CD4+ T cells, and B cells)." (PMID 36059530, 2022). "However, research on YBX3, an emerging member of the YBX family, in cancer development is limited." (PMID 36059530, 2022).
neurological disorders (1 paper, 2024). "The minimal overlap regions for CNV deletions containing YBX1 and YBX3 include loci beyond the gene of interest that are associated with monogenic neurological disorders and other diseases in humans." (PMID 39423228, 2024). "However, unlike the loci surrounding YBX1, none of the loss of function intolerant loci around YBX3 are known to cause monogenic neurological disease." (PMID 39423228, 2024).
vascular disorder (1 paper, 2026). A general term used to describe any disease affecting blood vessels]. "Here, we discovered that the Y-box factor ZONAB (ZO-1-associated nucleic acid binding protein; YBX3), a gene associated with risk loci for severe vascular disorders, regulates endothelial homeostasis and angiogenesis." (PMID 42274608, 2026).
YBX3 also shares sentences with these, for which no sentence is quoted: Lyme disease (15 papers); carditis (3); cholangiocarcinoma (3); colon adenocarcinoma (2); glioblastoma (2); kidney disease (2); lung adenocarcinoma (2); lung squamous cell carcinoma (2); thyroid carcinoma (2); Alzheimer disease (1); bladder urothelial carcinoma (1); cervical squamous cell carcinoma (1); chronic kidney disease (1); cystinosis (1); digestive system tumors (1); endocervical adenocarcinoma (1); esophageal carcinoma (1); familial visceral myopathy (1); fibrosis (1); germ cell tumours (1); joint disease (1); lung diseases (1); mantle cell lymphoma (1); metabolic disease (1); minimal change disease (1); mononucleosis (1); nasopharyngeal carcinoma (1); ovarian dysgerminomas (1); ovarian serous cystadenocarcinoma (1); pancreatic cancer (1).
A further 19 diseases each share a sentence with YBX3 in 1 paper.